TNF (tumor necrosis factor)
Diseases named in the same sentence as TNF in open-access papers (continued):
Sharing a sentence is not in itself a finding about the gene and the disease.
breast carcinoma (continued). "Of all inflammatory markers investigated, we found that ox-LDL, IL-1β, and TNF-α were significantly associated with breast cancer (model I) when adjusting for matching factors." (PMID 27391324, 2016). "Participants in the higher tertiles of ox-LDL and TNF-α were at lower risk of breast cancer compared to the first tertile, whereas the opposite was seen for IL-1β." (PMID 27391324, 2016). "Upregulation of TNF-α has been shown to be associated with increase metastatic potential and invasiveness in breast cancer." (PMID 27429011, 2016). "A high level of TNF-α is a characteristic of many malignant cancers, including breast cancers, and has frequently been associated with an aggressive behavior and a poor prognosis." (PMID 27042827, 2016). "Another study suggested that carriers of high-expression alleles of IL6-174 and TNF-308 were associated with poorer memory in breast cancer patients." (PMID 27701469, 2016). "The ox-LDL and TNF-α variables showed inverse associations, while IL-1β was associated with increased breast cancer risk." (PMID 27391324, 2016). "In recent studies of breast cancer survivors, key polymorphisms in TNF-related signaling pathways correlate with the severity of neurocognitive sequelae." (PMID 25909710, 2015). "In this prospective cohort study of 100 premenopausal female patients with early-stage breast cancer, we investigated associations between functional SNPs in IL10 and TNFα genes, previously implicated in breast cancer occurrence, spread and survival." (PMID 26112140, 2015). "Of all the tested single nucleotide polymorphisms, only TNFα -308G > A has revealed a prognostic capability for breast cancer survival." (PMID 26112140, 2015). "The purpose of this study was to assess the association between TNF-α-308G > A and breast cancer (BC) risk by subtype and the connection between genotypes and clinical features of BC." (PMID 26165253, 2015). "Some investigators found genetic evidence for association between IL10 -1082A > G, −819 T > C, −592A > C and TNFα -308G > A polymorphisms and breast cancer progression in different ethnic populations." (PMID 26112140, 2015). "For TNF c.-418 and c.-488 polymorphisms, an Indian study, reported that the AA genotype resulted in an increased breast cancer risk, which is also different from our results." (PMID 25559835, 2014). "TNF-α −308G > A polymorphism has been reported to alter the risk of several types of cancers, such as breast cancer, lung cancer, non-Hodgkin lymphomas, and prostate cancer." (PMID 25420786, 2014). "It has been shown that bortezomib inhibits proteasomal degradation of IκBα induced by cytokines (i.e., TNFα); however, IκBα was downregulated in both cell lines by bortezomib treatment, associated with enhanced phosphorylation in breast cancer cells." (PMID 24481412, 2014). "Various meta-analyses indicated that TNF-a 308A polymorphism was associated with an elevated risk of gastric cancer, breast cancer, cervical cancer and lung cancer." (PMID 24404201, 2014). "The SNPs within TNF-α promoter have been investigated widely in relation to breast cancer, and the most frequently studied variants are rs1800629 and rs361525, which have been observed to affect TNF-α transcriptional activity." (PMID 25010932, 2014). "Given the independence of circulating levels and main effects between 25OHD and TNFα, this observed synergistic association implies separate but inter-connecting pathways underlying the roles of the two analytes on the etiology of breast cancer subtypes." (PMID 24473087, 2014). "An anti-inflammatory compound, curcumin, has recently been demonstrated to reverse Warburg effect caused by Tumor Necrosis Factor (TNF) stimulation in breast cancer cells." (PMID 24626155, 2014). "The important roles of ER and PR in invasion and metastasis of breast cancer are probably associated with NF-κB and TNF-α expression." (PMID 24864130, 2014).
breast carcinoma (continued). "In this study, we focused on IL-6 and TNF-α due to their association with poor prognosis for breast cancer patients." (PMID 23372803, 2013). "In this study, we present data that suggest that loss of Trx1 or TR1 increases TNF-α-induced apoptosis in breast cancer cells by localizing phosphorylated ERK 1/2 to the nucleus in a PI3K-dependent manner." (PMID 24039713, 2013). "Specifically in breast cancer, studies in animal model systems have shown that TNFα exerted causative procancerous activities through a diverse set of mechanisms." (PMID 24369447, 2013). "TNFα is implicated in chronic inflammation and can support tumor growth and breast cancer progression." (PMID 23991131, 2013). "To elucidate the role of TR1 and Trx1 in tumor necrosis factor (TNF)-α-induced apoptosis in cancer cells, we examined the sensitivity of TR1- or Trx1-deficient breast cancer cells to TNF-α." (PMID 24039713, 2013). "Trx1-deficient breast cancer cells manifested a particularly high sensitivity to TNF-α-induced apoptosis." (PMID 24039713, 2013). "For example, prior studies have identified polymorphisms in TLR4 (rs4986790) and TNF (rs361525 and rs1800629) that affect breast cancer risk." (PMID 23634849, 2013). "TNF has been implicated in tumor regression, and there is some evidence that TNF genetic variants are associated with breast cancer risk." (PMID 23095343, 2012). "The results of our study indicate that significant associations exist between CCL2 & CCL5 and TNFα & IL-1β in breast cancer, along different stages of disease course." (PMID 21486440, 2011). "We provide evidence to a coordinated expression of the inflammatory chemokines CCL2 & CCL5 and the inflammatory cytokines TNFα & IL-1β in breast cancer, all having causative roles as tumor-promoting factors in this disease." (PMID 21486440, 2011). "This is in contrast to the recent report that TNFα stabilized Snail through NF-κB-dependent induction of CSN2 in breast cancer cells, which inhibited the association of Snail with GSK3β and thus suppressed its phosphorylation and degradation." (PMID 20661477, 2010). "Despite intensive study of the mechanisms of chemotherapeutic drug resistance in human breast cancer, few reports have systematically investigated the mechanisms that underlie resistance to the chemotherapy-sensitizing agent tumor necrosis factor (TNF)-α." (PMID 19087274, 2008). "The studies presented here reveal that high-level BP1 expression is associated with enhanced survival of breast cancer cells challenged with TNFα." (PMID 17854498, 2007). "TNF-α increases the susceptibility of breast cancer cells to chemotherapy by up-regulating TRAIL expression by promoter activation." (PMID 17592646, 2007). "Conversely, the TNFα signaling pathway via the NF-κB pathway exhibited a significant negative association with WNTHigh cells, aligning with previous findings suggesting that active β-catenin can attenuate transcriptional NF-κB activity in breast cancer." (PMID 41117706, 2026). "Consequently, obesity raised levels of TNF-α in the circulatory system, which raised the risk of breast cancer associated with insulin resistance and IL-6 production." (PMID 40584290, 2025). "Besides, we measured an increased association between CXCL8 and expression of TNF itself in breast cancer cell lines (R2 = 0.34) versus all cell lines (R2 = 0.01)." (PMID 40833805, 2025). "Moreover, a recent systematic review analyzing 15 studies in breast cancer patients receiving chemotherapy reported that IL-6, IL-1β, and TNF-α were associated with varying degrees of cognitive impairment." (PMID 41155372, 2025). "The use of IL-6 and TNF-alpha as prognostic biomarkers could enhance the personalization of treatment in breast cancer patients by tailoring it according to the risk associated with overall survival and potential therapeutic response." (PMID 40558287, 2025).
breast carcinoma (continued). "Additionally, significant decreases in TNF-α have been observed in physically active breast cancer survivors, possibly linked to concomitant reductions in fat mass and diminished activation of adipose tissue–associated inflammatory pathways." (PMID 41303335, 2025). "TNF-α, another cytokine implicated in breast cancer, plays a crucial role in three aspects." (PMID 40558287, 2025). "Interestingly, we identified many TNF-α pathway genes to associate significantly more strongly with CXCL8 when comparing breast cancer cell lines with the entire dataset (p = 0.02, paired t test)." (PMID 40833805, 2025). "According to subtype analyses, skimmianine’s PCNA- and TNF-α-associated anticancer effects may be more relevant in basal molecular subtypes and C2 immune subtypes of breast cancer." (PMID 40430573, 2025). "Similarly, TNF-α was strongly associated with all-cause mortality among all breast cancer survivors, with higher associations among postmenopausal cases and those with longer periods from blood draw to diagnosis." (PMID 39342063, 2024). "It was reported that TiO2 could induce apoptosis in breast cancer cell by interfering signaling pathways TiO2 cause ROS generation which activates the release of pro-inflammatory cytokines release such as TNF-α." (PMID 38827789, 2024). "The different outcomes may be associated with the different coculture cell types, breast cancer cell lines, or different TNF-α–mediated signaling pathways." (PMID 38457510, 2024). "However, Stat3 gene targets elevated in the Fyn neurodegeneration model included tnfrsf1a; its human homolog (TNFRSF1A) encodes a receptor for TNF-α (also known as TNF) and is associated with activation of the NF-κB pathway in breast cancer." (PMID 39641161, 2024). "However, both IL-1β and TNF-α exhibit paradoxical pro-tumor effects that are associated with metastasis in breast cancer." (PMID 39474419, 2024). "DNA methylation alterations of the tumor necrosis factor (TNF) gene may influence the risk of developing chronic breast pain in patients with breast cancer undergoing surgery." (PMID 39125894, 2024). "Although this still needs further investigation, exploratory analysis from a randomized controlled trial showed that having increased inflammatory markers of interleukin (IL)-8 and Tumor Necrosis Factor-alpha (TNF-α) at diagnosis was associated with an RDI < 85% in patients with breast cancer." (PMID 37173949, 2023). "According to several studies, raised levels of cytokine-mediated acute phase C-reactive protein, and pro-inflammatory cytokines, including IL-6, IL-1β, and TNF- α are found in breast cancer patients, documenting that breast cancer is associated with inflammation." (PMID 36978815, 2023). "Increased expression of TNF-α is associated with many cancers, most importantly with breast cancer." (PMID 36751235, 2023). "When conducting a systematic research review, Salignan’s team proved that increased symptoms of fatigue, especially in women in early stages of breast cancer, were caused by increased concentrations of IL-6 and TNF, and of IL-1β during chemotherapy, and of IL-6 during radiotherapy." (PMID 36834426, 2023). "TNFα is a most potent pro-inflammatory cytokine whose presence was associated with breast cancer progression, and possibly due to its chronic expression at the tumor sites, it is strongly connected to advanced malignancy in patients and in animal breast models." (PMID 37190183, 2023). "Our findings suggested that E-DII scores were positively associated with DepS risk among breast cancer patients, which might be mediated by TNF-α." (PMID 36615742, 2022). "Here, we demonstrated that TNF signaling components are likely to be enriched in TNBC or basal cell lines compared with their other counterparts from other subtypes, implying that TNF signaling expression may be linked to breast cancer aggressiveness." (PMID 34197030, 2022).
breast carcinoma (continued). "According to the analysis of the reasons, the abnormal immune function of breast cancer patients leads to the hyperfunction of B cells in the body, which promotes the secretion of inflammatory factors such as TNF-α, which increases the inflammatory response and causes systemic inflammatory response." (PMID 35783155, 2022). "Furthermore, the results demonstrated that DIM efficiently suppressed EMT processes by the inhibition of TNF‐α/TGF‐β‐associated signalling pathways in breast cancer cells." (PMID 35384373, 2022). "Our findings suggest that a pro-inflammatory diet is positively associated with breast cancer-related DepS, which may be mediated by TNF-α." (PMID 36615742, 2022). "Additionally, positive associations between IL-1β, TNF-α and DepS were also found in postoperative breast cancer patients untreated with adjuvant chemotherapy." (PMID 36615742, 2022). "While TNF-α has been implicated breast cancer growth, it may also function in the development of antitumor immune response." (PMID 35440077, 2022). "The stages of breast cancer caused clear differences in the levels of TNF-α and IL-19." (PMID 35928364, 2022). "In the fully adjusted model (which included BMI but not waist circumference), IL-6 was positively associated with breast cancer risk (continuous variable only, ORper SD increment = 1.33 (1.11–1.60)), as was TNF-α (ORper SD increment = 1.32 (1.11–1.58); ORQ4vsQ1 = 2.03 (1.26–3.26), P-trend = 0.006)." (PMID 35948877, 2022). "This analysis of seven inflammatory biomarkers and breast cancer risk in a case–control study in premenopausal women from Latin America showed that IL-6 and TNF-α were positively associated with breast cancer risk when accounting for adiposity and other breast cancer risk factors." (PMID 35948877, 2022). "Therefore, IL-10 inhibits the expression of aromatase in breast adipose tissue induced by TNF-α, thus reducing breast cancer risk." (PMID 34201776, 2021). "The association between resistin, TNF-α, IL-6, IL-8, and ER-α expression and breast cancer." (PMID 33517609, 2021). "As many proinflammatory cytokines, including IL-1β, IL-6, and TNF-α, have been strongly linked to breast cancer progression, their suppression could be a key mechanism mediating the chemoprotective role of phytoestrogens in this cancer." (PMID 35008370, 2021). "A study investigated if certain serum cytokine profiles (e.g., ILs, tumor necrosis factor alpha, interferon gamma) could be associated with the presence of CTCs in breast cancer patients." (PMID 33809315, 2021). "We investigated whether the mRNA expression of resistin, TNF- α, IL-6, IL-8, and ER-α in PBMCs are associated with breast cancer." (PMID 33517609, 2021). "Proinflammatory cytokines have a similar ambiguous role; high-dose interleukin-2 (IL-2) has been used to treat melanoma, whereas TNFα is associated with aggressive breast cancer biology, and its inhibitor, etanercept, is currently tested in the phase II clinical trial for metastatic breast cancer." (PMID 33457427, 2020). "In addition, recent preclinical studies showed that TNFR2 blockade was enough to reduce the progression of breast cancer cell lines treated with TNFα and that it promoted TNFα-associated lung cancer cell death." (PMID 32391269, 2020). "For example, TNF-α is implicated in immune responses in breast cancer and might therefore serve as a treatment target in triple negative breast cancer." (PMID 32756008, 2020). "Subsequently, to test whether class I HDACs are associated with TNF-α-induced apoptotic cell death in breast cancer cell lines, we examined cell viability after overexpression of each of the class I HDACs." (PMID 32455774, 2020). "The results of KEGG pathway enrichment analysis is supported by the results of drug association analysis, which showed that potential therapeutic target of brazilin against metastatic breast cancer cells (PB) are associated with tyrosine kinase inhibitors and TNFα inhibitors." (PMID 32986377, 2020).
breast carcinoma (continued). "The protective effect of anti-TNF therapy observed on breast cancer risk may have been confounded by unmeasured effects of non-steroidal anti-inflammatory drugs and other synthetic disease-modifying anti-rheumatic drugs in patients with autoimmune diseases." (PMID 32805626, 2020). "Moreover, in women with breast cancer, inflammation in the tumor microenvironment, with local elevation in the expression of proinflammatory cytokines (such as tumor necrosis factor-α), has also been associated with increased invasiveness and a poor prognosis." (PMID 32015762, 2020). "Also, Coulson associated the inhibition of progression with reduction of mammary tumor cell proliferation and of pSTAT3, TNFα and IL-6 in Losartan-treated group compared to control group." (PMID 32850009, 2020). "Macrophage-associated CLS has been linked to increased proinflammatory mediators (TNF-α, IL-1β, Cox-2) and aromatase expression, and may be an indicator of mammary tumor risk in rodent models." (PMID 32731638, 2020). "The TNF-α c.-308G>A (rs1800629) polymorphism was found to be associated with breast cancer risk in a study conducted in Mexico, and another Mexican study found associations between the RETN c.-225C>G (rs1862513) and CAP1 c.881G>A (rs35749351) polymorphisms and breast cancer risk." (PMID 30781715, 2019). "In conclusion, our results indicate that changes in inflammatory biomarkers (plasma MMP9 and TNFα) associated with breast cancer risk and survival in breast cancer survivors with low plasma 25(OH)D levels, supplemented with vitamin D3 depends on VDR SNPs (Cdx2, TaqI and BsmI) and haplotypes." (PMID 31167402, 2019). "Also, the level of ALCAM transcripts was associated with the expression of TNFα, NF-κB p50, IL-4, and intratumoral inflammation in breast cancer." (PMID 29315254, 2018). "Furthermore, studies of breast-cancer survivors reveal reduced hippocampal volumes and deficits in verbal memory performance that are associated with elevated circulating levels of TNF-α." (PMID 29515447, 2018). "In particular, tumor necrosis factor (TNF) signaling pathway was associated with paratumoral inflammatory change in breast cancer, and this inflammatory process could be detected by imaging." (PMID 30532215, 2018). "However this conclusion is opposed by our finding that high TNF-α was associated with increased breast cancer risk in premenopausal women." (PMID 28983080, 2017). "TNFα is another host factor that is implicated in breast cancer susceptibility." (PMID 28369883, 2017). "In this regard, high circulating levels of insulin like-growth factor I (IGF-I) increased the risk of breast cancer, while TNF-α prevented IGF-I-dependent DNA synthesis, leading cells into G0/G1 phase and avoiding them from entering the S phase of the cell cycle in MCF-7 cells." (PMID 29202842, 2017). "This may be linked to the evidence showing that TNF-α has an important implication in the course of breast cancer development, which could be the result of its ability to regulate signaling pathways involved in gene expression regulation." (PMID 29202842, 2017). "Clinical studies have reported that the increased levels of TNF-α mRNA among overweight/obese subjects are associated with increased risk of breast cancer risk and TNF-α expression in the peripheral blood mononuclear cells (PBMC) of obese subjects decreases after reduction in weight." (PMID 29088874, 2017). "We carried out a case-control study to prospectively assess whether pre-diagnostic levels of CRP, TNF-α, IL-6, leptin, and adiponectin in plasma are associated with risk of developing breast cancer." (PMID 28983080, 2017). "TNFα promoter polymorphisms are associated with breast cancer risk." (PMID 28369883, 2017). "The pre‐existing metabolic differences in normal breast epithelium and elevated levels of cytokines (e.g., IGF1 and TNFα) may determine susceptibility to oncogenic transformation and thereby increase breast cancer risk in some women." (PMID 28369883, 2017).